U6 (U6 spliceosomal RNA )
Synonyms: LOC124904715
Gene: Small nuclear RNA gene on chromosome 1 (43,023,549 to 43,023,637, reverse strand). Ensembl gene ENSG00000283136.
Gene Ontology:
Molecular function: U4 snRNA binding
Biological process: formation of quadruple SL/U4/U5/U6 snRNP; spliceosomal tri-snRNP complex assembly
Cellular component: U4/U6 x U5 tri-snRNP complex; U6 snRNP
Homologues: Orthologues: chimpanzee U6 (100% identical), macaque U6 (94% identical), rabbit U6 (89% identical), mouse Gm25935 (85% identical), guinea pig U6 (84% identical), dog U6 (74% identical). Paralogues in human: RNU6-480P (90% identical), RNU6-1082P (89% identical), RNU6-94P (89% identical), RNU6-140P (88% identical), RNU6-16P (88% identical), RNU6-33P (88% identical), RNU6-1 (87% identical), RNU6-1038P (87% identical), RNU6-1099P (87% identical), RNU6-1144P (87% identical), RNU6-116P (87% identical), RNU6-2 (87% identical), and 1287 more.